EPCAM (epithelial cell adhesion molecule)
Diseases named in the same sentence as EPCAM in open-access papers (continued):
Sharing a sentence is not in itself a finding about the gene and the disease.
squamous cell carcinoma (52 papers, 2007 to 2026). A carcinoma arising from squamous epithelial cells. "It is of note that other authors had described reciprocal results and found associations between high-level EpCAM expression and tumor progression in renal cell or between low EpCAM expression and tumor progression in squamous cell carcinomas." (PMID 38786342, 2024). "EpCAM (also known as CD326) is deemed as a cancer-associated marker, as it is always overexpressed in many human adenocarcinomas and squamous cell carcinomas." (PMID 34900726, 2021). "Squamous cell carcinomas of different sites of origin made up for most tumor categories with a higher rate of TROP2 positivity than seen for EpCAM." (PMID 38786342, 2024). "The lower positivity rate of EpCAM as compared to CKpan in squamous cell carcinomas obviously reflects the rather low level of EpCAM expression in normal squamous epithelium, while CKpan staining is usually strong in these tissues." (PMID 38786342, 2024). "EpCAM is frequently upregulated in primary tumors and metastases, particularly in adenocarcinomas, certain squamous cell carcinomas, and others." (PMID 37303738, 2023). "We also performed an in vitro investigation on the effect of lncCDH5-3:3 silencing and overexpression on the cell cycle, proliferation, apoptosis, and expression of CDH1 and EPCAM in the adenocarcinoma and squamous cell carcinoma cell lines." (PMID 35159188, 2022). "Overexpression of the epithelial cell adhesion molecule (EpCAM) is found on a variety of human adenocarcinomas and squamous cell carcinomas." (PMID 36182995, 2022). "We also acknowledge that the CTCs detection system relied on CTCs epithelial markers procession, cell homogeneity, and potential difference of detection between adenocarcinoma and squamous cell carcinoma due to difference in expression of EpCAM." (PMID 35804307, 2022). "Researchers have also created a scFv with affinity to the epithelial cell adhesion molecule EpCAM, that is overexpressed in most adenocarcinomas and squamous cell carcinomas." (PMID 36077739, 2022). "The epithelial cell adhesion molecule (EpCAM, CD326) is expressed by most epithelial tissues, and its expression is up-regulated on certain tumor types, including adenocarcinomas and squamous cell carcinomas." (PMID 34943898, 2021). "Methods: using different squamous cell carcinoma cell lines, we developed an isolation protocol exploiting highly efficient EpCAM-targeting magnetic beads for automated CTC enrichment by the IsoMAG IMS system." (PMID 34829387, 2021). "In the current study, three distinct subpopulations of EPCAM+ epithelial tumor cells were clustered including adenocarcinoma‐derived glandular cells, squamous cell carcinoma, and neuroendocrine carcinoma cells." (PMID 34185421, 2021). "Neoplasms from the thyroid and parathyroid glands, squamous carcinoma, and adenocarcinomas from the lungs were EPCAM-positive." (PMID 33003511, 2020). "Thyroid and neuroendocrine neoplasms also displayed EPCAM expression, but squamous carcinoma, hepatocellular tumors, lymphomas, the CNS, and soft tissue tumors were EPCAM-negative." (PMID 33003511, 2020). "The expression of EpCAM is significantly elevated in a number of human adenocarcinomas as well as squamous cell carcinomas." (PMID 32046162, 2020). "It is well-known that adenocarcinoma is more radio-resistant than squamous cell carcinoma at other anatomical sites and EpCAM is essentially expressed in all adenocarcinomas." (PMID 31361893, 2019). "Because expression of EpCAM in squamous cell carcinoma is not frequent, there are few reports that dealt with expression of EpCAM in squamous cell carcinomas." (PMID 31361893, 2019). "Epithelial cell adhesion molecule (EpCAM) is a promising biomarker for squamous cell carcinoma (SCC) of the uterine cervix, because it is over-expressed in various cancers of epithelial origin." (PMID 29202724, 2017).
squamous cell carcinoma (continued). "EpCAM is frequently highly expressed on most solid tumors, including carcinomas of the breast, ovarian, lung, colon, and pancreatic cancer and in squamous cell carcinoma of the head and neck, suggesting its potential as a therapeutic target." (PMID 25960617, 2015). "Several EpCAM-target antibodies have been used in the clinic to treat malignant ascites and squamous cell carcinomas of the head and neck, as well." (PMID 25960617, 2015). "We also noted a tendency toward higher EpCAM expression in cases of adenocarcinoma as compared to squamous cell carcinoma, which is consistent with previous data." (PMID 23959111, 2014). "EpCAM+ cells were detected in 60 % of the patients, and the number of these cells was higher in patients with adenocarcinoma than patients with squamous cell carcinoma and was also higher in patients with less advanced disease." (PMID 23959111, 2014). "On average, high-level and mostly homogenous EpCAM expression was found on 85% of adenocarcinoma and on 72% of squamous cell carcinoma." (PMID 17211480, 2007). "In summary, a fair number of EpCAM-directed immunotherapies are under development as therapeutics exploiting the frequent expression of the antigen on adeno and squamous cell carcinoma." (PMID 17211480, 2007). "The strong link between poor differentiation and high EpCAM expression in squamous cell carcinomas from different sites of origin may suggest a role of EpCAM upregulation for the progression of these tumors." (PMID 38786342, 2024). "The comparison with TROP2 revealed that EpCAM is less commonly expressed in squamous cell carcinomas but more abundant in most other epithelial neoplasms especially in germ cell tumors, neuroendocrine neoplasms, renal cell tumors, and in gastrointestinal adenocarcinomas." (PMID 38786342, 2024). "Furthermore, the expression of EpCAM in squamous carcinomas is correlated with increased cellular proliferation and decreased differentiation." (PMID 37543570, 2023). "Additionally, 48 h after KO, adenocarcinoma and squamous carcinoma (H1703) cells have increased expressions of EpCAM." (PMID 35159188, 2022). "Delta median fluorescent intensity (Delta MFI; mean ± SD for Gaussian and median and range for non-Gaussian data) of staining of a goat polyclonal anti-EpCAM antibody (R&D EpCAM) on feline mammary carcinoma, squamous cell carcinoma and fibrosarcoma cell lines as assessed by flow cytometry." (PMID 33614766, 2021). "EpCAM is also considered a marker of carcinogenesis, because it is over-expressed in many tumors of epithelial origin, even tumors arising from tissue which normally lack expression of the protein, such as squamous cell carcinoma." (PMID 33614766, 2021). "QPCR further confirmed that organoids expressed latent EBV genes, as well as displayed distinct cell borders [integrin and epithelial cell-adhesion molecule (EpCAM) staining] and cytoplasmic keratinization (pan-cytokeratin staining), which are histologic characteristics of squamous cell carcinoma." (PMID 33732646, 2021). "EpCAM participates as a cell adhesion and cell signaling molecule, and its overexpression negatively correlates with survival rates in gallbladder cancer, ampullary carcinoma, and squamous cell carcinoma (SCC) of the head and neck." (PMID 22482828, 2012). "Tumor epithelial clusters expressed canonical squamous carcinoma markers such as CLDN1, LAMB3, TP63, CDKN2A, EPCAM, and SERPINB2, validating their malignant identity, while stromal and immune subsets displayed expected transcriptional programs." (PMID 41510303, 2025). "A comparison of EpCAM and TROP2 revealed a higher rate of TROP2 positivity in squamous cell carcinomas and lower rates in many gastrointestinal adenocarcinomas, testicular germ cell tumors, neuroendocrine neoplasms, and renal cell tumors." (PMID 38786342, 2024).
squamous cell carcinoma (continued). "The comparison with CKpan revealed that EpCAM staining is particularly common in seminomas and in neuroendocrine neoplasms, while TROP2 is more commonly expressed in squamous cell carcinomas." (PMID 38786342, 2024). "A different series of cell surface markers (EpCAM, VCAM, ITGAV, and ITGB3) along with single-cell RNA sequencing (sc-RNAseq) was applied to identify E/M states in squamous cell carcinoma of the skin." (PMID 37259089, 2023). "Tongue squamous cell carcinoma cells with UBE2C silencing exhibit lowered expression of the cancer stemness markers ALDH1/A2, CD44, CD166 and EpCAM, indicating the role of UBE2C in controlling the cancer stemness." (PMID 36551544, 2022). "For head-and-neck cancer cells, the human hypopharyngeal squamous cell carcinoma cell line FaDu-luc2 and the oral squamous cell carcinoma cell line OSC-19 showed similar intermediate EpCAM expression." (PMID 27842504, 2016). "Although little is known about epithelial cell adhesion molecule (EpCAM) gene expression in NSCLC, a few studies have reported the upregulation of EpCAM in NSCLC cell lines and specimens, notably in squamous cell carcinoma." (PMID 24094028, 2013). "Tissue microarray blocks acquired from 164 cases of NSCLC, including 100 cases of adenocarcinoma (AdC) and 64 of squamous cell carcinoma (SCC), were examined by immunohistochemical staining for EpCAM, and TROP2." (PMID 22482828, 2012). "Although, EpCAM is absent or weakly expressed in the vast majority of healthy epithelial squamous cells, it is strongly expressed in squamous cell carcinomas." (PMID 37543570, 2023). "Based on the expression of cell surface markers, EpCAM-negative squamous carcinoma cells were separated into six discrete subpopulations of the E/M cells presenting different degrees of mesenchymal differentiation." (PMID 37259089, 2023). "Another previous study demonstrated that an anti-EpCAM toxin-conjugated antibody Oportuzumab monatox (also termed VB4-845) was effective against squamous cell carcinomas of the head and neck and non-muscle invasive bladder cancer, and well-tolerated in clinical trials (phase I and II)." (PMID 33154781, 2020). "A similar negative correlation between EpCAM expression and survival as previously observed by the group for breast and gall bladder cancer was also now observed with ampullary carcinoma of the pancreas and for squamous cell cancer of head and neck." (PMID 17211480, 2007). "EpCAM, similarly, is absent on normal squamous epithelia but shows increased expression during progression from CIN I to CIN III and is detectable in some squamous carcinomas." (PMID 41154384, 2025).
non-small cell lung carcinoma (47 papers, 2012 to 2026). A group of at least three distinct histological types of lung cancer, including non-small cell squamous cell carcinoma, adenocarcinoma, and large cell carcinoma. "Detection of non-small cell lung cancer (NSCLC) using an antibody against epithelial cell adhesion molecule (EpCAM) in captured CTCs has low sensitivity; the loss of epithelial markers leads to underestimation of CTCs with mesenchymal phenotype." (PMID 28432274, 2017). "In line with previous results in non-small cell lung cancer, EpCAM-independent detection of CTC show a high sensitivity." (PMID 36869231, 2023). "Curcumin also enhances the effects of cisplatin by targeting the CSCs CD166+/EpCAM+ subpopulation in non-small cell lung cancer cell lines (NSCLC) by p21- and cyclin D1-mediated tumor cell inhibition." (PMID 32127962, 2020). "Although clinically relevant, the detection rates of EpCAM positive CTCs in non-small cell lung cancer (NSCLC) are surprisingly low." (PMID 31092882, 2019). "The numbers of ldEVs and leukocytes in EpCAM-enriched 7.5 mL blood samples of 25 healthy individuals, 25 metastatic prostates, 25 colorectal, and 25 non-small cell lung cancer patients were determined and are presented in box plots." (PMID 31434250, 2019). "Nevertheless, some non-small cell lung cancer (NSCLC) tumor cells have a lower expression of EpCAM and are less frequently detected by CellSearch." (PMID 29352248, 2018). "Antibodies against EpCAM have previously been used to visualize micrometastases in lymph nodes of papillary thyroid cancer and non-small-cell lung cancer by immunohistochemistry." (PMID 28820475, 2017). "Here, we present and discuss epithelial cell adhesion molecule-dependent and -independent capture of CTCs in non-small cell lung cancer (NSCLC) and the clinical relevance of CTC detection and characterization." (PMID 26442219, 2015). "Importantly, longitudinal biopsy samples from ALK-rearranged non-small cell lung cancer patients with cancer progression revealed elevated expression of E-cadherin and EpCAM during chemotherapy." (PMID 41679471, 2026). "The epithelial cell adhesion molecule (EpCAM) may represent a target for CAR T-cell therapy as EpCAM is overexpressed in about 50% of non-small cell lung cancer and their metastases." (PMID 39358663, 2024). "Here, we used the open source imaging program Automatic CTC Classification, Enumeration and PhenoTyping (ACCEPT) to analyze all DAPI+ nuclei in EpCAM-enriched blood samples obtained from 192 metastatic non-small cell lung cancer (NSCLC) patients and 162 controls." (PMID 30308977, 2018). "Integrating antibodies against EpCAM, HER2, and EGFR in CTC isolation platforms improved capture rates and provided a more comprehensive profile of CTC populations in breast and non-small cell lung cancer patients." (PMID 40076201, 2025). "In approximately 30% of metastatic non-small-cell lung cancer (NSCLC) cases, CTCs can be detected using this EpCAM-targeting platform." (PMID 39337304, 2024). "In non-small cell lung cancer cell lines it was also shown that ZEB1 downregulated its target genes, e.g. EpCAM (epithelial cell adhesion molecule) by globally decreasing H3K27ac marks on these genes." (PMID 24840099, 2014). "Therefore, we have found a potential immunotherapeutic strategy, which was the combination therapy with EpCAM/CD3 BsAb and MUC-1/CD3 BsAb for the treatment of non-small cell lung cancer." (PMID 34522164, 2021). "Hence, a triple-positive marker, EPCAM+/CD166+/CD44+, has recently been described in the human non-small cell lung cancer cell line." (PMID 32391123, 2020). "Clinical feasibility was investigated by analyzing whole blood specimens from non-small cell lung cancer (NSCLC) patients and cholangiocarcinoma patient, using the epithelial marker EPCAM and the epithelial–mesenchymal transition (EMT) biomarkers vimentin and MET." (PMID 32486306, 2020).
non-small cell lung carcinoma (continued). "Little is known about EpCAM and TROP2 gene expression in non-small cell lung carcinoma (NSCLC)." (PMID 22482828, 2012). "Datasets of single-cell RNAseq from patients with non-small-cell lung cancer (NSCLC) who were smokers were first analyzed to identify clusters of cells using the expression of known markers for cell types, such as tumor cells with EPCAM and leukocytes with PTRPC (CD45)." (PMID 37444590, 2023). "CTC expressing both epithelial and mesenchymal markers, have been identified in patients with breast and non-small cell lung cancer suggesting that CTC may undergo an epithelial to mesenchymal transition (EMT) and thus exhibit reduced expression of epithelial markers such EpCAM and CK." (PMID 26498594, 2015). "Therefore, we investigated EpCAM-positive and -negative CTCs in non-small cell lung cancer (NSCLC) patients at different stages, assessed the clinical value of these CTCs and explored their capacity in the following CSC model." (PMID 26317979, 2015). "Clinical characteristics of patients with squamous cell carcinoma of the head and neck (SCCHN), CUP tumor of the head and neck, and non-small cell lung carcinoma (NSCLC) assessed for CTC isolation using cmHsp70.1 mAb- and EpCAM mAb-functionalized magnetic beads." (PMID 30443493, 2018). "In some cancer types, such as non-small-cell lung cancer (NSCLC) patients, it was even found that the quantity of EpCAM-negative CTCs was significantly larger than EpCAM-positive CTCs30." (PMID 34803167, 2021).
metastatic disease (40 papers, 2003 to 2025). "Firstly, additional research is essential to elucidate the precise mechanisms underlying the suppression of EpCAM expression in metastatic tumors, as it relates to the promotion of tumor migration and invasion." (PMID 38187284, 2024). "An anti-cytokeratin and anti-EpCAM stain were performed on these tissue foci to confirm human origin and verify target expression by metastatic tumors (arrowheads), respectively." (PMID 39199591, 2024). "We also found higher frequencies of homozygous deletions for EPCAM and EPAS1 in MMR-d primary tumors and for EPCAM in MMR-d metastatic tumors." (PMID 36675550, 2023). "CTCs are released from a primary or metastatic tumor and shed into the peripheral blood, where they can be isolated by size selection or by targeting surface proteins such as EpCAM, MUC1, or HER2." (PMID 36430255, 2022). "The epithelial cell adhesion molecule (EpCAM) is a transmembrane glycoprotein that is overexpressed on the majority of primary and metastatic tumors, and is involved in gene regulation, cell proliferation, and cancer cell differentiation and renewal." (PMID 34727233, 2021). "In this retrospective pilot study, the feasibility of the epithelial cell adhesion molecule (EpCAM) as an imaging target for lymph node (LN) metastatic disease of urothelial cell carcinoma (UCC) of the bladder was investigated." (PMID 28820475, 2017). "Analysis of the peripheral blood of these mice at different stages of tumorigenesis revealed an increase in mesenchymal (EpCAM−/GFP+) and biphenotypic (EpCAM+/GFP+) CTCs correlating with metastatic disease." (PMID 28544498, 2017). "Given the results from the present study, it is possible that the level of EpCAM positivity is underestimated in primary and metastatic tumors using conventional antibodies." (PMID 23460885, 2013). "Among the selected candidates, MUC4 was significantly up-regulated in both primary and metastatic samples of fast-progressing patients, whereas HTRA2 and RAB25 were significantly elevated only in primary samples and EPCAM only in metastatic tumors of the fast-progressing group." (PMID 36527824, 2023). "Nevertheless, CTCs might undergo an epithelial-to-mesenchymal transition in metastatic disease after which their EpCAM expression is downregulated." (PMID 36143225, 2022). "The downregulation of EpCAM in CTCs compared with primary and metastatic tumors suggests that EpCAM expression might be transient and related to EMT." (PMID 32764280, 2020). "This may explain the relative low number and frequency of CTCs detected with EpCAM-based assays, particularly when compared to other metastatic diseases and to EpCAM-independent assays." (PMID 32290064, 2020). "EpCAM-positive CTC might serve as a biomarker for metastatic disease, and thus represent the urgently needed marker to identify patients with high requirement for adjuvant treatment." (PMID 29163804, 2017). "Interestingly, the number of CD133+EpCAM+ double-positive cells per 1 ml of blood was higher in patients with metastatic disease, although this result was observed in only three patients." (PMID 23959111, 2014). "We found an elevated proportion and number of CD133+ cells in the blood of patients with metastatic disease, while cells expressing EpCAM were significantly depleted in patients with metastases (median value: 0.0015 vs. 0.0046 % in patients without metastases; p = 0.012)." (PMID 23959111, 2014). "Among metastatic tumors from the GENIE database, the frequency of homozygous deletions at EPCAM (21.4% vs. 0%, Bonferroni-adjusted p = 4.2 × 10−16) was significantly higher in MMR-d tumors." (PMID 36675550, 2023). "The function of EpCAM and the interactive regulation between Slug and EpCAM during cells undergoing EMT to form metastatic tumors in cervical cancer still need more research to be further clarified." (PMID 33691694, 2021).